Y_RNA (Y RNA )
Gene: Miscellaneous RNA gene on chromosome 17 (69,985,986 to 69,986,094, forward strand). Ensembl gene ENSG00000199801.
Homologues: Orthologues: chimpanzee Y_RNA (95% identical), macaque Y_RNA (87% identical). Paralogues in human: Y_RNA (82% identical), Y_RNA (81% identical), RNY1P5 (80% identical), Y_RNA (80% identical), RNY1 (78% identical), RNY1P1 (78% identical), Y_RNA (78% identical), Y_RNA (77% identical), Y_RNA (76% identical), Y_RNA (75% identical), RNY1P7 (74% identical), Y_RNA (74% identical), and 94 more.